MMP2 (matrix metallopeptidase 2)
Diseases named in the same sentence as MMP2 in open-access papers (continued):
Sharing a sentence is not in itself a finding about the gene and the disease.
cancer (continued). "C1q treatment significantly enhanced the expressions of MMP2 and 9, which suggested C1q might augment cancer progression by up-regulating these MMPs." (PMID 29559654, 2018). "Because it is known that MMPs play a major role in promoting metastasis of cancer cells, we first examined the proteolytic activity and expression level of MMP-2 and MMP-9 in ISLA-treated and untreated HT1080 CM." (PMID 30618749, 2018). "MMP-2 plays a crucial role in the migration and invasion of cancer cells." (PMID 29385675, 2018). "MMP-2/9 degrades extracellular matrix, which plays a critical role in cancer metastasis." (PMID 30581390, 2018). "Strategies to selectively target MMP-2 activity in other tissues or the delivery of cancer-specific payloads containing MMP-2 inhibitors may allow for the inhibition of this potent proteinase in other steps of the metastatic cascade." (PMID 29874869, 2018). "Furthermore, curcumin has been demonstrated to inhibit cancer progression by suppressing MMP-2 activity." (PMID 29385675, 2018). "This approach allowed us to visualize MMP-2 activities in cancer cells and their microenvironment." (PMID 29466303, 2018). "For example, it is now recognized that many MMPs, including MMP-2/-9, can be protective in cancer and that their upregulation may be involved in processes aimed at eliminating abnormal tumor cells." (PMID 30248101, 2018). "EGCG has been found to affect several cancer-related proteins including Cyclin-dependent kinase inhibitor p27 (p27), Bcl-2 or Bcr-Abl oncoproteins, Bax, matrix metalloproteinases (MMP-2 and MMP-9) the androgen receptor, EGF receptor, Activator proteins 1(AP1), and some cell cycle regulators." (PMID 30701033, 2018). "Notably, CEP55 was shown to support the invasion and metastasis of cancer cells via upregulating MMP2 expression." (PMID 30096813, 2018). "Among MMPs, MMP-2 and MMP-9 upregulation has been associated with invasive tumors, and they are considered to play an important role in invasion and metastasis formation of cancer cells." (PMID 30235821, 2018). "Importantly, the annexin A2 acts as a vehicle for the trafficking of CD147-positive EVs during tumor-stromal interactions and govern the production of MMP-2 from fibroblasts, which enhance the migration potential of cancer cells." (PMID 30322133, 2018). "Matrix Metallopeptidase 2 (MMP2) activity is responsible for cancer cell migration." (PMID 29734730, 2018). "Therefore, the production of MMP-2/9 is thought to directly promote invasion and migration of cancer cells." (PMID 28729634, 2017). "MMP-2 and -9 play essential and varied roles in the progression of several types of cancers." (PMID 29233192, 2017). "MMP2 can degrade the type collagen to facilitate the metastasis of cancer cells." (PMID 29262634, 2017). "Therefore, we first confirmed the inhibitory effects of PEITC on MMP-9 and MMP-2 in various cancer cells." (PMID 28969043, 2017). "Some cancer cell lines express both MMP-2 and MMP-9, whereas some cells express only MMP-2." (PMID 28606135, 2017). "Above results indicated the inhibitory effects of DBL on cancer cell metastasis may be due to the suppression of MMP-2 and -9 expression." (PMID 28350337, 2017). "Importantly, the expression of MMP2 in these cases was detected in the myoepithelial cells lining the basement membrane of tubuloalveolar structures in benign tumours, while malignant tumours showed MMP2 expression in the neoplastic cells themselves." (PMID 28531107, 2017). "Moreover, previous studies also reported that the PI3K-AKT pathway can participate in the invasion and metastasis of cancer cells through increasing expression levels of gelatinases (MMP-2 and MMP-9)." (PMID 28945763, 2017). "Therefore, the inhibition of migration mediated by MMP-2 or MMP-9 can putatively provide a preventive measure against cancer metastasis." (PMID 29285298, 2017). "MMP2 was involved in many pathways in cancer, and it existed in many proteoglycans in cancer." (PMID 29050278, 2017).
cancer (continued). "MMP2 gelatinase activities in GA cancer tissues were visibly higher than those in normal tissues." (PMID 29285307, 2017). "Cancer cells secrete MMPs such as MMP2 and MMP9 to promote invasion into surrounding tissues." (PMID 27974675, 2017). "Our recent study reveals that MMP‐2 overexpression is crucial for human BC invasion, whereas inhibition of MMP‐2 expression by the anti‐cancer agent isorhapontigenin (ISO) dramatically attenuated both BC invasion in vitro and highly invasive BC formation in vivo." (PMID 28846829, 2017). "Furthermore, MMP-2, a member of the matrix metalloproteinase family, contributes to cancer owing to its importantrole in degrading structural components of the extracellular matrix, thus paving ways for cells to migrate and invade to further locations." (PMID 28915666, 2017). "TNF-α could induce Twist1 expression and overexpression of Twist1 could promote further metastasis, which increased the expression of MMP-9, MMP-2, CD44v6 and vimentin in cancer cells." (PMID 28774312, 2017). "Cancer cells secrete MMPs (eg, MMP-2 and MMP-9) to degrade the extracellular matrices." (PMID 28938623, 2017). "The results of wound healing and Boyden chamber assays showed that sub-IC50 (sub-lethal) concentrations of BPIQ cause a significant inhibition of migration in H1299 cells accompanied with downregulating the activity of MMP-2 and -9, the motility index of cancer cells." (PMID 28286419, 2017). "Despite the unexpected findings of invasion assay, we assessed by RT-qPCR that some FOXM1 downstream targets involved in metastasis, cancer progression, and cisplatin resistance, such as MMP2 and MACC1, were specifically down-regulated in OSPC2 cells after FOXM1 silencing." (PMID 28482906, 2017). "Furthermore, several studies reported that OPN enhanced the migration and invasion of cancer cells by up-regulating MMP-2 and MMP-9 activities via NF-κB pathway." (PMID 29228698, 2017). "Overexpression of MMP-2 has been detected in various types of cancer." (PMID 26942004, 2016). "Our previous study demonstrated that ACC-derived CAFs might promote cancer invasion by expressing MMP2 and CXCL12 in vivo, but it remained unclear how CAFs promote ACC cell invasion." (PMID 26954362, 2016). "In addition, FN and MMP-2 expression, which play an important role on cell motility in various cancer cells, were dose-dependently decreased by LY2109761." (PMID 26637807, 2016). "Furthermore, by using specific inhibitors of various cancer-related signaling pathways, we showed that 14-3-3β-induced up-regulation of MMP2 and MMP9 was dependent on PI3K/Akt/NF-κB signaling pathway." (PMID 26730736, 2016). "Basigin-2, also known as CD147, is a transmembrane glycoprotein present on the cancer cell surface belonging to the immunoglobulin superfamily, which was found to induce expression of matrix metalloproteinases (MMPs), particular MMP-2 and MMP-9 in fibroblasts or tumor cells." (PMID 27042161, 2016). "Alternatively, different cancers might preferentially use either the MMP2 and MMP9, or MMP14 targeting pathways." (PMID 27789576, 2016). "Therefore, this cellular process provides a multiple targets for the development of therapeutic agents to inhibit cancer invasion and metastasis 1, such as MMP‐2, ‐9, and VEGF." (PMID 27605356, 2016). "Another study suggested that CCL2/CCR2 axis could promote cancer metastasis by up-regulation of MMP2/9 through ERK1/2 signaling pathway." (PMID 27409666, 2016). "Given that it remains unclear how miR-204 affects the cancer invasion machinery, we decided to investigate whether miR-204 inhibits MMP2 and MMP9 targeting to invadopodia by decreasing cellular levels of Rab40b." (PMID 27789576, 2016). "Besides, in SK-Hep 1 human hepatoma cells, the treatment of the two compounds dose dependently suppressed cancer cell adhesion, invasion, and migration through downregulating matrix metalloproteinase (MMP)-2/-9 at a transcriptional level." (PMID 26978396, 2016).
cancer (continued). "MMP-2 is also involved in integrin αVβ3-mediated signaling in cancer cells." (PMID 27695098, 2016). "Furthermore, the expression levels of MMP-2 (molecular weight 63 kDa) and MMP-9 (molecular weight 92 kDa), representative MMPs associated with the migration of cancer cells, were downregulated following berberine treatment." (PMID 25634589, 2015). "Furthermore, C2 ceramide was reported to suppress cancer invasiveness through downregulating MMP-2 expression." (PMID 25792190, 2015). "Polymorphisms in promoter regions of MMP genes might be related to the susceptibility of digestive cancers, with a role in cancer development for MMP1 and MMP7, and a role of protection against cancer for MMP2 and MMP9." (PMID 25596746, 2015). "Here, we present evidence from cell and animal models to demonstrate that stabilization of Bcl-2 protein by phosphorylation at Serine 87 (pBcl-2-S87) via PXN-mediated ERK activation is responsible for cancer cell invasiveness and occurs via upregulation of MMP2 expression." (PMID 25826088, 2015). "MMPs have been recognized as involved in cancer invasion and metastasis, especially MMP2 and MMP9." (PMID 26714817, 2015). "Furthermore, the expression of SERPINE1 and MMP-2 was reduced in tumors formed with cancer cells and leptin shRNA obASCs, relative to tumors formed with cancer cells and control shRNA obASCs." (PMID 26286584, 2015). "In addition, MMP2 downregulation through the NF-κB-dependent pathway has been documented in cancer cells." (PMID 26388610, 2015). "Because our study found that MMP-2 is up-regulated at the mRNA level in MCF-7 cells treated with CAA-CM and MMP-2 is a proteinase which has been verified to promote cancer metastasis, we detected MMP-2 in MCF-7 cells treated with CAA-CM and CM plus with IGFBP-2." (PMID 25747684, 2015). "We suggest that using selective MMP-2 inhibitors in OSCC that strongly express MMP-2 may achieve better results than obtained from previous clinical trials of MMPIs in cancer therapy." (PMID 26155333, 2015). "To find a molecular explanation for the increased invasion as a function of PBK/TOPK expression, we examined vital downstream effectors, such as the matrix metalloproteinases, MMP-2 and -9, which together are known to play a key role in metastatic development in human cancer patients." (PMID 25909225, 2015). "Furthermore, it has been shown that MMP2 expression is closely correlated with VEGF signaling in cancer cell growth, invasion and metastasis." (PMID 25954957, 2015). "RAGE activation gives origin to an intracellular cascade leading to the activation of the nuclear factor-κB (NF-κB) pathway and also of mitogen activated protein kinase (MAPK) and type IV collagenase (MMP-2/-9) which are fundamental for cancer cell characteristic." (PMID 26798204, 2015). "MMP-2 (gelatinase A) and MMP-9 (gelatinase B) are cancer-associated zinc-dependent endopeptidases." (PMID 25563361, 2015). "In addition to Erk1/2 signaling, other studies have shown that the expression of MMP-2/9 is also regulated by the STAT3 pathway, and activation of STAT3 is also associated with drug resistance of cancer cells." (PMID 26501276, 2015). "In stem cells and cancer cells, MMP2 and MMP9 are regulated by cytokines such as TGFβ2 and TNFα." (PMID 25774514, 2015).
cancer (continued). "In addition, inhibition of AKT phosphorylation has been correlated with the inhibition of cancer cell invasion by reducing MMP-2 and MMP-9 expression." (PMID 25647359, 2015). "Because MMP-2 and MMP-9, as well as MMP-7, are known to be the downstream targets of β-catenin, significant inhibition in the level of β-catenin by embelin may inhibit MMP-2 activity and cancer cell migration." (PMID 26252009, 2015). "It has been reported that TLR9 signaling could directly promote cancer cell invasion via, at least in part, AP-1 (jun proto-oncogene) activated MMP-2 secretion in HB cells." (PMID 26087186, 2015). "Nevertheless, the elevated expression of SERPINE1 and MMP-2 correlated with the increased incidence of metastatic lesions in the lung and liver of mice injected with a mixture of obASCs and cancer cells, compared to mice that received cancer cells alone or cancer cells mixed with lnASCs." (PMID 26286584, 2015). "Cancer cell invasion may require the secretion of MMPs such as MMP-2 and MMP-9 to degrade the matrigel." (PMID 25798926, 2015). "MMP-9 and MMP-2 expression levels are significantly elevated in a range of carcinomas." (PMID 26098839, 2015). "Furthermore, the Met-F-AEA in combination with URB597 reduces EGF induced invasion and also downregulates MMP2 secretion, which mediates the invasiveness of cancer cells by aiding them to degrade the ECM and metastasize." (PMID 24811863, 2014). "Membrane-bound MMP-14 is required to activate MMP-2 and is known to be involved in cancer invasion." (PMID 24959847, 2014). "Our observations indicate that the expression of MMP-2 in normal mucosa of CRC patients could also be relevant as well to the outcome in cancer cells." (PMID 24395652, 2014). "Based on the established role of MMP-2 in cancer metastasis, we selected MMP-2 for further study." (PMID 25149542, 2014). "After being secreted by the fibroblast, pro-MMP-2 may bind to the cancer cells possibly to the MT-MMPs situated on the surface of their plasma membrane." (PMID 24591757, 2014). "This and our data demonstrate that uPAR and HSP70/MRJ complex may promote matrix degradation, as knockdown of HSP70 and/or MRJ decreased the mRNA levels of mmp2 and mmp9, two important cancer invasion related genes." (PMID 25175595, 2014). "Our results show that fibrocytes are key components of the metastatic foci and can promote invasion and colonization of cancer cells through expression of MMP2, and suggest that fibrocytes might be constituents of CAFs." (PMID 25326065, 2014). "Thus, an alteration in claudin-4 expression appears to play a role in the invasiveness of cancer cells, by modulating the barrier function of tight junctions or by mediating MMP-2 and -9 activity." (PMID 25120725, 2014). "Besides, our results indicated that solanine can also inhibit the process of metastasis by downregulating the expression of cancer cells migration related proteases, MMP-2 and MMP-9." (PMID 24949471, 2014). "Since the degradation of the basement membrane by MMP-2 is likely an essential step for cancer invasion, it is necessary to study whether α1-PDX mediates the activity of other MMPs." (PMID 24944664, 2014). "In addition, three putative targets (MMP1, MMP2, and MMP7) of marketing anti-cancer drugs were reported to be associated with NSCLC." (PMID 24429698, 2014). "Forced BTG1 overexpression decreased the expression of PI3K, Akt, Bcl-xL, survivin, VEGF, and MMP-2 mRNA and protein; these are target factors in our cancer research, which have clear roles in the regulation of cellular apoptosis and proliferation, and thus were examined in this study." (PMID 24084718, 2013). "In addition, Hop knockdown also led to the loss of matrix metalloproteinase 2 (MMP-2) and a decrease in cancer cell migration, also consonant with a permissive role for Hop in cancer progression." (PMID 24278769, 2013).
cancer (continued). "However, there is early selection of HER-2 positive cancer cells which leads to androgen independence and to increased expression of MMP-2 activity in the micrometastasis." (PMID 23766685, 2013). "In addition, we provide evidence that miR-124-3p appears to play an important role in epithelial mesenchymal transfer (EMT), and modulates the expression of genes which promote cancer metastasis, such as MMP2, MMP9, c-Met." (PMID 24180482, 2013). "MMP-2 has been suggested to play a critical role in cancer metastasis, and the up-regulation of MMP-2 is associated with increased invasion and a poor prognosis in cancer." (PMID 23786715, 2013). "Based on previous studies, we inferred that TRPV2 activity may be mediated by the direct regulation of key proteins, such as MMP2, which are used by cancer cells for invasion." (PMID 24223658, 2013). "And MMP-2 is a typical factor in cancer cell invasion and metastasis." (PMID 23405233, 2013). "Using pharmacological inhibitors, siRNAs, and blocking antibodies, we demonstrated that the MMP-1 and MMP-2 matrix metalloproteinases, known to participate in late stages of cancer invasion and metastasis, are responsible for this enhancement of early migratory capacity." (PMID 23675494, 2013). "Among the MMP family members, MMP-2 and -9 are important for cancer invasion." (PMID 23599733, 2013). "Rac1 was reported to increase the secretion and activity of MMP-2 in cancer cells." (PMID 23408967, 2013). "In addition, a key finding from this study was that spiclomazine suppressed migration and invasion of cancer cells through down-regulation of MMP-2/9." (PMID 23840452, 2013). "Overexpression of various MMPs in particular MMP-2 (gelatinase A), -9 (gelatinase B) and MT1-MMP (collagenase), has been detected in a majority of squamous cervical carcinomas, and these enzymes have been implicated in cancer progression and poor prognosis." (PMID 23967226, 2013). "MMP-2 and -9 are the principle MMPs expressed by cancer cells." (PMID 23840452, 2013). "We tested the expressions of B7-H3 and MMP-2 protein in 45 pancreatic surgical resected cancer samples; meanwhile, the clinicopathological data of enrolled patients were obtained for correlation analysis to obtain their relationship with pancreatic cancer progress." (PMID 23947693, 2013). "Consequently, the less adherent cancer cells initially cease to proliferate and are arrested in the G1 phase of the cell cycle, accompanied by decreased matrix metalloproteinase-2 (MMP-2) expression." (PMID 23545855, 2013). "In cancer cells, MMP-2 and MMP-9 are controlled by their endogenous inhibitors TIMP-1 and TIMP-2." (PMID 23878609, 2013). "MMP-2 and -9 are key factors in cancer cell invasion and metastasis in vitro." (PMID 23599733, 2013). "Numerous studies have demonstrated that MMP2 is critical in cancer development and progression." (PMID 24223658, 2013). "In cancer cells that are proliferating in the bone marrow, for mechanical reasons, the cells grow into the intertrabecular space and as a result the inhibition of MMP-2 decreases and secondary dissemination is possible." (PMID 23227342, 2012). "In other studies, both p38 and JNK modulated MMP-2 production in cancer cells." (PMID 23320037, 2012). "Thus, our mass spectrometry and immunoassay data suggest that KLKs are probably secreted by cancer cells, while MMP2 is mainly stromatogenic." (PMID 22408128, 2012). "Furthermore, a previous study demonstrated significant correlation between NM inhibition of Matrigel invasion and NM modulation of the MMP-2 and -9 activity of the female cancer cells lines studied." (PMID 22736175, 2012). "These diverse activities may account for the role of MMP-2, a pivotal matrix metalloprotease that control cancer cell motility and invasion." (PMID 22962598, 2012).